ARMS2 (age-related maculopathy susceptibility 2)
Synonyms: LOC387715; ARMD8
Tractability: No criterion of Open Targets' tractability assessment is met for any kind of drug.
Gene: Protein-coding gene on chromosome 10 (122,454,653 to 122,457,352, forward strand). Ensembl gene ENSG00000254636.
Subcellular location: Cytoplasm
Subcellular location (Human Protein Atlas): End piece; Principal piece
Gene Ontology:
Molecular function: protein binding
Biological process: retina homeostasis
Cellular component: mitochondrion; photoreceptor inner segment; cytoplasm
Genetic constraint (gnomAD): Loss-of-function variants: 4 observed, 4.16 expected, observed/expected ratio (o/e) 0.96, 90% interval 0.46 to 1.82. That is too few expected variants to judge how well the gene tolerates losing a copy. Missense variants: 92 observed, 124.14 expected, observed/expected ratio (o/e) 0.74, 90% interval 0.62 to 0.88. Synonymous variants: 47 observed, 50.91 expected, observed/expected ratio (o/e) 0.92, 90% interval 0.73 to 1.18.
Homologues: Orthologues: chimpanzee ARMS2 (98% identical).
Diseases named in the same sentence as ARMS2 in open-access papers:
ARMS2 is named in the same sentence as 44 diseases in open-access papers, as found by Europe PMC text mining. Sharing a sentence is not in itself a finding about the gene and the disease. The quoted sentences say what the papers report.
age-related macular degeneration (55 papers, 2007 to 2025). Age-related loss of vision in the central portion of the retina (macula), secondary to retinal degeneration. "Among more than 100 associated loci, the most prominent are complement factor H (CFH) and age-related maculopathy susceptibility 2/high temperature requirement A serine peptidase 1 (ARMS2/HTRA1)." (PMID 41516080, 2025). "According to our study, the SNPs with high OR values for AMD exposure on cataract included ARMS2 (rs3750847, age-related maculopathy susceptibility 2)." (PMID 38674349, 2024). "A strong association has been shown between all stages of AMD and the genetic variation in age-related maculopathy susceptibility (ARMS2)." (PMID 39064267, 2024). "The two most significant of these are polymorphisms in the CFH and ARMS2 (age-related maculopathy susceptibility 2) genes." (PMID 30591665, 2018). "ARMS2, age-related maculopathy susceptibility 2 rs10490924; CFH, complement factor H rs1061170; SD, standard deviation." (PMID 25905023, 2015). "This locus includes the age-related maculopathy susceptibility (ARMS2) gene and the gene encoding for the high-temperature requirement factor A of serine peptidase 1 (HTRA1)." (PMID 24369445, 2013). "Polymorphisms in the ARMS2 gene lesion: Distribution and Genotypes in neovascular Age-Related Macular Degeneration (nAMD), Polypoidal Choroidal Vasculopathy, and Controls in the northern Chinese Population." (PMID 23326481, 2013). "Polymorphisms in the ARMS2 gene lesion: Distribution and Allele in neovascular Age-Related Macular Degeneration (nAMD), Polypoidal Choroidal Vasculopathy, and Controls in the northern Chinese Population." (PMID 23326481, 2013). "The ARMS2/HTRA1 genes at the 10q26 locus have been associated with risk of age-related macular degeneration (AMD), with the most significantly associated variants being A69S (rs10490924), del443ins54 (EU427539) and rs11200638." (PMID 23592919, 2013). "Another genetic locus identified was the age-related maculopathy susceptibility gene (ARMS2 [A69S, rs10490924]) on chromosome 10q26." (PMID 24600618, 2012). "Clinical details of the typical neovascular age-related macular degeneration (tAMD) patients stratified by the genotype of rs10490924 in the age-related maculopathy susceptibility 2 (ARMS2) gene." (PMID 21541271, 2011). "Although the inflammation in AMD is largely mediated through complement-associated pathways, such as CFH, CFI, C2, CFB, and C3, other mechanisms have also been reported, including age-related maculopathy susceptibility (ARMS2), which acts through a matrix metalloproteinase inhibitor." (PMID 36011777, 2022). "On the other hand, previously reported disease-associated CNVs were detected using this approach like, for example, well-known deletions spanning IRGM, LCE3 and ARMS2 loci, which have been respectively associated to Crohn's disease, psoriasis and age-related macular degeneration." (PMID 23844243, 2013). "The CD subtype of AMD was significantly associated with current smoking as well as variants in the complement factor H (CFH), age-related maculopathy susceptibility 2 (ARMS2), complement factor B/complement component 2 (CFB/C2), complement component 3 (C3), and apolipoprotein E (APOE) genes." (PMID 22933840, 2012). "Serine protease (HTRA1) and age-related macular degeneration susceptibility factor 2 (ARMS2) are both found in retinal tissues, and their serum expression is significantly elevated in AMD patients." (PMID 40365539, 2025). "Therefore, we conducted for the first time in a sample of the Algerian population a replication study to analyse the frequency of CFI rs10033900 and ARMS2 rs3750846 polymorphisms and to evaluate the effect of these two polymorphisms on exudative age related macular degeneration." (PMID 36059931, 2022). "The complement factor H (CFH) and the age-related macular susceptibility 2 (ARMS2) variants Y402H and A69S are major genetic risk and progression factors in age-related macular degeneration (AMD)." (PMID 21151600, 2010).
age-related macular degeneration (continued). "In conclusion, identifying genetic variations in ARMS2, VEGFA, TNFRSF1A, TNFRSF1B, and IL1B1 provides valuable insights into the susceptibility to and treatment outcomes for age-related macular degeneration." (PMID 39273697, 2024). "We found two different loci in AbdAge (rs932274, p = 1E−10) and Pancreas Accelerated Age (rs2672597, p = 3.9E−9) respectively that are close to genes implicated in age-related macular degeneration (PLEKHA1, ARMS2, HTRA1)." (PMID 35418184, 2022). "It has been reported that ARMS2 and CFH are two major genes susceptible to age-related macular degeneration (AMD) through genome-wide association studies." (PMID 33920794, 2021). "Apart from CFH gene polymorphisms, ARMS2 gene SNP rs10490924 is associated with CSC, which suggests genetic overlap between age related macular degeneration (AMD) and CSC." (PMID 35052395, 2021). "Genome-wide association studies have identified genetic variation at the ARMS2/HTRA1 locus as a risk factor for the development and progression of age-related macular degeneration (AMD)." (PMID 32345717, 2020). "The purpose of this study was to investigate the association of ARMS2/HTRA1 and CFH SNPs with early age-related maculopathy (ARM) in a Han Chinese cohort." (PMID 23687431, 2013). "Single nucleotide polymorphisms (SNPs) in the tightly linked LOC387715/ARMS2 and HTRA1 genes have been associated with age-related macular degeneration (AMD)." (PMID 19065273, 2008). "A putative transcription factor binding site of the HTRA1 gene in the 10q26 region was shown to confer significant risk for choroidal neovascularization in age related macular degeneration (AMD) and SNPs rs1061170, rs3753394 in CFH and rs10490924 in ARMS2/LOC387715 showed significant association." (PMID 21067572, 2010). "In mCNV, a recent meta-GWAS uncovered a new locus (near TEX29/LINC02337) as a shared genetic susceptibility with age-related macular degeneration (AMD), along with other risk variants at CETP and the ARMS2 regions." (PMID 40909333, 2025). "What are the independent and combined associations of the 2 most common genetic risk loci for age-related macular degeneration (AMD)—chromosomes 1 (CFH-CFHR5) and 10 (ARMS2/HTRA1)—with disease progression?" (PMID 35113155, 2022). "The two most common genetic contributors to age-related macular degeneration (AMD), a leading cause of irreversible vision loss worldwide, are variants associated with CFH-CFHR5 on chromosome 1 (Chr1) and ARMS2/HTRA1 on chromosome 10 (Chr10)." (PMID 33273512, 2020). "Blood samples from all subjects were genotyped for major age-related macular degeneration (AMD)-associated single nucleotide polymorphisms (SNPs) the major AMD-associated SNPs; CFH Y402H rs1061170, CFH I62V rs800292, ARMS2 A69S rs10490924." (PMID 30596689, 2018). "It lies next to the ARMS2/HTRA1 genes in a region of chromosome 10q26, where single nucleotide variants have been strongly associated with age-related macular degeneration (AMD), the commonest cause of blindness in Western populations." (PMID 27416785, 2016). "Single nucleotide polymorphisms (SNPs) of age-related maculopathy susceptibility protein 2/HtrA serine peptidase 1 (ARMS2/HTRA1) and complement factor H (CFH) have been reported to be associated with age-related macular degeneration (AMD)." (PMID 23687431, 2013). "Major genetic factors for age-related macular degeneration (AMD) have recently been identified as susceptibility risk factors, including variants in the CFH gene and the ARMS2 LOC387715/HTRA1locus." (PMID 19806217, 2009). "Polymorphisms in the ARMS2/HTRA1 locus on chromosome 10 enhance the risk of geographic atrophy and macular neovascularization, the advanced forms of age-related macular degeneration (AMD)." (PMID 40832922, 2025). "The aim of this study was to explore whether there are interactions between genetic (ARMS2/HTRA1) and environmental factors (cigarette smoking) in the pathogenesis of age-related macular degeneration (AMD)." (PMID 35138344, 2022).
geographic atrophy (10 papers, 2008 to 2025). "Here, we analyzed association between variants in CFH, C3 and ARMS2 and disease progression of geographic atrophy (GA) due to AMD." (PMID 19823576, 2009). "Interestingly, the ARMS2/HTRA1 locus was significantly more associated to neovascular disease as compared to geographic atrophy." (PMID 31934346, 2020). "Clinical trials targeting proteins encoded by the AMD-associated genomic loci C3, CFB, CFI, CFH, and ARMS2/HTRA1 are currently ongoing, and a phase III clinical trial for C3 inhibition recently showed a modest reduction of lesion growth in geographic atrophy." (PMID 36108770, 2022). "CFH, ARMS2/HTRA1 and C3 genes have been reported to increase the risk of progression from intermediate drusen to large drusen and from large drusen to geographic atrophy and neovascularization." (PMID 25893111, 2015). "Our data confirm the association between advanced AMD (both geographic atrophy and CNV) and the 10q26 SNPs rs11200638 (HTRA1 promoter) and rs10490924 (LOC387715/ARMS2 A69S), independent of the CFH Y402H polymorphism." (PMID 18682806, 2008). "We genotyped three SNPs, rs1061170 (exon 9, CFH), rs11200638 (HTRA1 promoter, −512 bp), and rs10490924 (6.6 kb upstream of HTRA1 in LOC387715/ARMS2) in 333 cases with advanced AMD (choroidal neovascularization [CNV] and geographic atrophy) and 171 age-matched examined controls." (PMID 18682806, 2008).
Hypertension (6 papers, 2011 to 2025). The presence of chronic increased pressure in the systemic arterial system. "However, four meaningfully distinct clusters of patients were identified that were most strongly differentiated by their cardiovascular health status (histories of hypercholesterolemia and hypertension), and the alleles of ARMS2/HTRA1 rs1049331." (PMID 21682878, 2011). "However, Clusters 1 and 3 would represent a higher opportunity target sub-population of AMD patients, as they in total represent 50.2% of the neovascular AMD population, and tend to have high blood pressure in combination with a high likelihood of carrying the ARMS2/HTRA1 TT genotype." (PMID 21682878, 2011). "Of these, 4,799 subjects have complete data on the following variables: early AMD, any AMD, gender, smoking, age, hypertension, diabetes, hyperlipidaemia, CKD, CFH rs10801555 and ARMS2 rs3750847." (PMID 25786237, 2015).
Polypoidal choroidal vasculopathy (5 papers, 2011 to 2021). The presence of aneurysmal 'polypoidal' lesions in the choroidal vasculature. "Age-related maculopathy susceptibility 2(ARMS2) was suggested to be associated with neovascular age-related macular degeneration (nAMD) and polypoidal choroidal vasculopathy (PCV) in multiple genetic studies in Caucasians and Japanese." (PMID 23326481, 2013). "Clinical details of polypoidal choroidal vasculopathy (PCV) patients stratified by the genotype of rs10490924 in the age-related maculopathy susceptibility 2 (ARMS2) gene." (PMID 21541271, 2011).
macular degeneration (3 papers, 2013 to 2024). Loss of vision in the central portion of the retina (macula), secondary to retinal degeneration. "The remaining annotations covered polymorphic pseudogenes either linked to a provisional phenotype (e.g. GUF1), or multifactorial diseases (e.g. CYP3A5), or with late onset diseases such as macular degeneration (e.g. ARMS2), retinitis pigmentosa and azoospermia or oligospermia, OR2W3." (PMID 39488654, 2024).
Atrophy (2 papers, 2021 to 2025). Any weakening or degeneration, especially through lack of use. "The size of atrophy at baseline and risk alleles for the ARMS2 variant accounted for a significant amount of unique variance (p = 0.003 and 0.032, respectively)." (PMID 40065020, 2025).
Hypercholesterolemia (2 papers, 2010 to 2011). An increased concentration of cholesterol in the blood. "ORs were adjusted for age, gender, tobacco smoking, hypercholesterolemia, and CFH and ARMS2 genotypes." (PMID 20664795, 2010).
hyperlipidaemia (2 papers, 2015). "The most predictive model for typical CNV included age, hyperlipidemia, spherical equivalent as measured in phakic eyes only, and ARMS2 rs10490924." (PMID 26171855, 2015). "The most predictive disease model for exudative AMD included age, spherical equivalent, smoking, CFH rs800292, and ARMS2 rs10490924 while that for typical CNV included age, hyperlipidemia, spherical equivalent, and ARMS2 rs10490924." (PMID 26171855, 2015).
myopia (2 papers, 2021 to 2022). "Based on our results, ARMS2 (rs10490924) and CFH (rs1061170) SNPs are associated with response to ranibizumab in high myopia patients with CNV." (PMID 34834388, 2021).
Alzheimer disease (1 paper, 2023). A progressive, neurodegenerative disease characterized by loss of function and death of nerve cells in several areas of the brain leading to loss of cognitive function such as memory and language. "Age-related maculopathy susceptibility protein 2 (ARMS2) is speculated to be involved in various age-related diseases, including AMD and Alzheimer’s disease." (PMID 36911400, 2023).
atrial fibrillation (1 paper, 2025). A disorder characterized by an electrocardiographic finding of a supraventricular arrhythmia characterized by the replacement of consistent P waves by rapid oscillations or fibrillatory waves that vary in size, shape and timing and are accompanied by an irregular ventricular response. "The WMH TWAS also identified genes associated with AD (ARMS2), atrial fibrillation (NEURL and GJC1), innate immunity (EFTUD2), and apoptosis and neurodevelopment (PDCD7, FBXO31, and ClpX)." (PMID 40141087, 2025).
cerebrovascular diseases (1 paper, 2023). "The variant rs10490924 in the ARMS2 gene and various systemic diseases, such as chronic respiratory diseases and cerebrovascular diseases, were found to be significantly associated with the risk of AMD development." (PMID 36911400, 2023).
diabetic retinopathy (1 paper, 2020). "High levels of hs-CRP are reported to be found in patients with diabetic retinopathy, AMD, and AMD high-risk variants of ARMS2/HTRA1 SNPs." (PMID 32503322, 2020).
glaucoma (1 paper, 2013). Increased pressure in the eyeball due to obstruction of the outflow of aqueous humor. "In the current study, the previously reported AMD associations, CFH and ARMS2, were readily detected as AMD associated loci using the glaucoma cohort as the control, with allele frequencies similar to those reported in other studies." (PMID 23536807, 2013).
macular dystrophies (1 paper, 2015). "Initial studies focused on HTRA1 because its overexpression might destroy the integrity of Bruch's membrane and lead to neovascularization, whereas ARMS2 protein was recently found to bind several matrix proteins that had been demonstrated to cause AMD or play roles in macular dystrophies." (PMID 25883802, 2015).
retinal degeneration (1 paper, 2025). Degeneration of the retina. "At the genetic level, mutations in genes such as complement factor H (CFH) and age-related maculopathy susceptibility 2 (ARMS2) have been identified as key risk factors for retinal degeneration, particularly in the context of AMD." (PMID 40428167, 2025).
Stroke (1 paper, 2023). Sudden impairment of blood flow to a part of the brain due to occlusion or rupture of an artery to the brain. "SDD were found to be significantly associated with lower high-density lipoprotein, cardiovascular disease, stroke, and the ARMS2 allele compared to AMD patients with drusen only." (PMID 38003879, 2023).
cardiovascular disease (4 papers, 2014 to 2023). "Older age, underweight BMI, cardiovascular disease history, higher alcohol intake and ARMS2 rs3750847 homozygous genetic loci were associated with an increased risk of incident early AMD." (PMID 29891972, 2018). "Systemic risk factors for six-year incident early AMD include underweight BMI, cardiovascular disease history, heavy alcohol intake and ARMS2 rs3750847 homozygous genetic loci." (PMID 29891972, 2018). "In the multivariate model, age, cardiovascular disease history, underweight BMI, heavy alcohol intake and ARMS2 rs3750847 homozygous genetic loci carrier remained significantly associated with the incident early AMD (P < 0.05 for all)." (PMID 29891972, 2018).
cancer (2 papers, 2023 to 2024). A tumor composed of atypical neoplastic, often pleomorphic cells that invade other tissues. "The exact function of the other genes in the top rank, FAM174A, ARRDC2, and ARMS2, remained unknown in ATO or cancer research." (PMID 37251921, 2023).
ARMS2 also shares sentences with these, for which no sentence is quoted: neovascular age-related macular degeneration (4 papers); diabetes (3); age (2); blinding disorder (2); hyperthyroidism (2); migraine (2); psoriasis (2); Azoospermia (1); Blindness (1); central serous chorioretinopathy (1); choroidal neovascularization (1); Crohn disease (1); hemochromatosis (1); immune disorders (1); ischemic stroke (1); kidney disease (1); Legionnaires' disease (1); Mendelian diseases (1); metabolic disease (1); Obesity (1); oligospermia (1); preeclampsia (1); retinitis pigmentosa (1); sarcoidosis (1); type II membranoproliferative glomerulonephritis (1).